SOX15 (SRY-box transcription factor 15)
Diseases named in the same sentence as SOX15 in open-access papers:
SOX15 is named in the same sentence as 30 diseases in open-access papers, as found by Europe PMC text mining. Sharing a sentence is not in itself a finding about the gene and the disease. The quoted sentences say what the papers report.
prostate carcinoma (6 papers, 2019 to 2025). A carcinoma that arises from epithelial cells of the prostate gland. "For instance, both PPP4R1L pseudogene and SOX15 are DE in prostate cancer and associated with hsa-miR-375." (PMID 31029062, 2019). "In prostate cancer, SOX15 functions as a tumor suppressor by upregulating AOC1, which reduces the proliferation and migration of prostate cancer through the activation of reactive oxygen species and ferroptosis." (PMID 38331879, 2024). "We also verified the sensitivity of two prostate cancer cell lines to ferroptosis inducer ML210 after knocking down SOX15." (PMID 35922412, 2022). "SOX15 inhibits the proliferation of glioma and prostate cancer." (PMID 39889187, 2025). "SOX15, as a transcription factor, has been widely demonstrated to inhibit tumor growth through the Wnt/β-catenin pathway and to function with miR-96 to regulate androgen receptor signals during prostate cancer progression." (PMID 35922412, 2022). "The results showed that only the expression of SOX15 in prostate cancer was consistent with AOC1." (PMID 35922412, 2022). "PPP4R1L and SOX15 are significantly co-expressed (Pearson correlation coefficient = 0.51, P-value < 2.2 × 10−16) in tumor tissue but much less correlated in normal controls in prostate cancer (Pearson correlation coefficient = 0.24, P-value = 0.09)." (PMID 31029062, 2019). "Targeting AOC1 and SOX15 may be promising for the treatment of prostate cancer." (PMID 35922412, 2022). "SOX15 transcription enhances the function of AOC1 to modulate ferroptosis and the progression of prostate cancer." (PMID 38164286, 2024). "Thus, the SOX15/AOC1/ROS axis might be a promising therapeutic target for prostate cancer." (PMID 35922412, 2022). "Both SOX15 and PPP4R1L are likely regulated by hsa-miR-375 based on the TCGA prostate cancer dataset." (PMID 31029062, 2019). "In summary, AOC1 depletion was able to accelerate the progression of prostate cancer cells, which was inhibited after simultaneously overexpressing SOX15, further demonstrating the mechanism of action of the SOX15/AOC1/ferroptosis axis in the modulation of prostate cancer development." (PMID 35922412, 2022). "In the present study, we demonstrated that SOX15 positively regulates AOC1 expression and that AOC1 has a tumor suppressor function in prostate cancer by downregulating the proliferation and migration of prostate cancer cells via the decomposition of spermidine." (PMID 35922412, 2022). "This study innovatively demonstrates that the transcription factor SOX15 can positively regulate AOC1 expression in prostate cancer, whereas ROS generated by the breakdown of spermidine by AOC1 can promote ferroptosis, thus playing an important role in inhibiting prostate cancer progression." (PMID 35922412, 2022).
glioma (5 papers, 2019 to 2026). A benign or malignant brain and spinal cord tumor that arises from glial cells (astrocytes, oligodendrocytes, ependymal cells). "However, for SOX15, a high degree of agreement between the mRNA and protein expression has been shown in pancreatic and colorectal cancers as well as in gliomas." (PMID 34603557, 2021). "CircVPS8 enhances glioma CSC viability, proliferation, and stemness, and suppresses ferroptosis by scaffolding MKRN1, SOX15, and HNF4A." (PMID 41601687, 2026). "For example, SOX15 is related to pancreatic tumors, esophagus tumors and embryonal cell carcinoma, while CXCL5 is related to laryngeal cancer and glioma and TLX1 is related to leukemia." (PMID 34691933, 2019). "Surprisingly, apart from SOX15, all MRGs are significantly correlated with the WHO grade of glioma." (PMID 40873641, 2025).
pancreatic ductal adenocarcinoma (4 papers, 2014 to 2023). An infiltrating adenocarcinoma that arises from the epithelial cells of the pancreas. "We recently identified SOX15 (also known as SOX20) as a potential tumor suppressor gene negatively associated with the Wnt/β-catenin pathway in pancreatic ductal adenocarcinoma (PDAC)." (PMID 25594027, 2014). "Previous work in pancreatic ductal adenocarcinoma has demonstrated that Sox15 is a potential tumor suppressor of the Wnt/β-catenin signaling pathway." (PMID 36579891, 2022). "Another study has indicated SOX15 repressed tumor formation in pancreatic ductal adenocarcinoma via the block of the Wnt/β-catenin signaling pathway." (PMID 31516388, 2019). "SOX15 serves as a potential tumor suppressor gene and is negatively associated with the development of pancreatic ductal adenocarcinoma through the Wnt/B-catenin pathway." (PMID 38132479, 2023). "SOX15, despite being relatively understudied compared to other SOX family members, demonstrates potential significance in regulating proliferation and acting as a tumor suppressor in specific cancer types, such as testicular embryonic cancer and pancreatic ductal adenocarcinoma." (PMID 38132479, 2023).
breast carcinoma (3 papers, 2022 to 2025). "SOX15 is positively regulated in four sets of lung cancer and in one of leukemia, and negatively regulated in a set of breast cancer." (PMID 36101460, 2022). "The 12 protein-coding genes upregulated in positive margin group included several well-known tumor markers for breast cancer (EEF1A2, EPHA6, FOXN4, SOX15)." (PMID 38038766, 2024). "In addition, we also detected the effects of 15 TFs on the proliferation function of breast cancer cells, among which knockdown of SOX6, SOX15, or CEBPG significantly inhibited the proliferation of Hs578T and BT549 cells, respectively." (PMID 40397381, 2025).
embryonal cell carcinoma (2 papers, 2016 to 2019). "We found a correlation between PIM1/2 expression and VENTX, SOX15, UTF1, NANOG, POU5F1P4, POU5F1P3, and POU5F1B expression in male germ cell tumors." (PMID 27901106, 2016).
lung carcinoma (2 papers, 2022 to 2024). "In fact, high levels of Twist and CD133 as well as low levels of E-cadherin, together with high nuclear b-catenin and low Sox15, have been proposed as diagnostic markers in lung cancer." (PMID 39443981, 2024).
pancreatic cancer (2 papers, 2014 to 2022). "We also summarized our recent finding of the relatively understudied SOX member, SOX15, as a potential tumor suppressor gene frequently inactivated in pancreatic cancer." (PMID 25594027, 2014). "Finally, we summarize our recent identification of SOX15 as a candidate tumor suppressor in pancreatic cancer and propose several research avenues to pursue to further delineate the emerging role of SOX15 in development and carcinogenesis." (PMID 25594027, 2014). "Meanwhile, Sox15 has been discovered to be the new TSG within esophageal and pancreatic cancers, and it may regulate the WNT/β-catenin pathway." (PMID 35392235, 2022).
colon cancer (1 paper, 2021). "Following this initial report, other studies have associated aberrant SOX15 expression with other kinds of tumors such as gastric, endometrial, and colon cancer." (PMID 34603557, 2021).
endometriosis (1 paper, 2016). The growth of functional endometrial tissue in anatomic sites outside the uterine body. "In conclusion, the results reported herein suggest that in endometriosis SOX15 and TWIST1 may be stemness-related markers as their expression correlates with OCT4 expression." (PMID 27881125, 2016). "Immunohistochemical analysis was used to determine stromal and epithelial expression of OCT4, SOX15, TWIST1 and DCAMLK1 in endometriosis patient (EP) endometrium (n = 69) and endometriotic tissue (n = 90) and in control endometrium (n = 50)." (PMID 27881125, 2016). "In conclusion, epithelial TWIST1, SOX15, and OCT4 are overexpressed in endometriotic tissue compared to EP endometrium of paired and unpaired endometriosis samples." (PMID 27881125, 2016). "71.7% (33/46) of endometriotic samples of the endometriosis cohort showing positive epithelial expression of OCT4 simultaneously showed positive epithelial staining for SOX15 (data not shown)." (PMID 27881125, 2016). "Thus we also analyzed a potential correlation and coexpression of OCT4 and SOX15, since SOX15 protein expression has never been studied in endometriosis." (PMID 27881125, 2016). "The aim of this study was to determine the presence and distribution of the stemness-related factors OCT4, SOX15, TWIST1 and DCAMLK1 in women with and without endometriosis." (PMID 27881125, 2016). "SOX15 for example strongly cooperates with OCT4 on the canonical pathway and has not been investigated in endometriosis so far." (PMID 27881125, 2016).
esophageal cancer (1 paper, 2022). A primary or metastatic malignant neoplasm involving the esophagus. "The SOX15 gene was demonstrated to be a tumor-suppressing gene, downregulating the Wnt/β-catenin pathway in esophageal cancer." (PMID 35328735, 2022).
Intellectual disability (1 paper, 2023). "These sites were screened through Geno2MP medical phenotypes, revealing novel SOX15 R104G associated with musculature abnormality and SOX8 R159G with intellectual disability." (PMID 36672963, 2023).
liver cancer (1 paper, 2022). An epithelial or non-epithelial malignant neoplasm that arises from the liver. "Moreover, the methylation status of Sox15 was a factor that independently predicted OS for liver cancer cases." (PMID 35392235, 2022).
papillary thyroid carcinoma (1 paper, 2021). "Our results indicate that SOX15 gene expression is associated with the pathogenesis of papillary thyroid carcinoma (PTC), and the epigenetic control of the SOX15 gene is regulated by miRNAs rather than by promoter methylation." (PMID 34603557, 2021).
pulmonary diseases (1 paper, 2017). "In the other hand, the -613C>T change, present only in the TCCT haplotype, caused the appearance of putative binding sites for SOX15 and for MAFB, which have been associated to pulmonary diseases." (PMID 29088248, 2017).
thyroid (1 paper, 2021). "The results of the present study indicate that the correlation between the miRNAs and SOX15 warrants further research to reveal their role and detailed mechanism in thyroid carcinogenesis." (PMID 34603557, 2021). "Deciphering the role and mutual interaction of SOX15 with specific miRNAs will certainly help to provide further insight implicating the cellular signals and pathways involved in thyroid carcinogenesis." (PMID 34603557, 2021).
thyroid cancer (1 paper, 2021). "There is only a single report in the literature which investigates miR-147b in thyroid carcinoma in association with SOX15." (PMID 34603557, 2021). "In the present study, to understand the epigenetic regulation of SOX15, we focused to investigate SOX15 expression in association with promoter methylation and expression of four different miRNAs in thyroid carcinoma." (PMID 34603557, 2021). "However, the role of SOX15 and its association with miRNAs in thyroid cancer has not been investigated thoroughly." (PMID 34603557, 2021). "In view of lack of studies on the function of SOX proteins in thyroid cancer, we believe that our data suggest a role for SOX15 and increased miR-182, miR-183, and miR-375 levels in the tumor samples." (PMID 34603557, 2021).
thyroid tumor (1 paper, 2021). A benign or malignant neoplasm affecting the thyroid gland. "The expression level of the SOX15 gene was analyzed in 49 pairs of thyroid tumors and adjacent noncancerous tissues." (PMID 34603557, 2021). "In this study, qRT-PCR was used to investigate the expression levels of the SOX15 gene and of miR-182, miR-183, miR-375, and miR-96 in thyroid tumors and adjacent noncancerous tissues." (PMID 34603557, 2021).
tumor (15 papers, 2014 to 2025). "According to the findings, a reduced Sox15 level predicted poorer patient survival and was associated with the tumor size." (PMID 35392235, 2022). "Therefore, we investigated promoter methylation of the SOX15 gene in PTC tumor cells in association with its expression levels." (PMID 34603557, 2021). "The expression of SOX12 was higher in the tumor cell subgroup compared to normal subgroup, whereas other SOX transcripts, including SOX2, SOX5, SOX9, SOX11, and SOX15, had low expression in tumor clusters." (PMID 40593465, 2025). "Tumor weight was significantly smaller in the Sox15-transfected mice compared to that in the vector-transfected mice." (PMID 35392235, 2022). "The tumor-suppressive function of Sox15 is mediated by downregulating the Wnt pathway and its target genes." (PMID 35392235, 2022). "In paired, primary HCC samples from patients, both Sox15 mRNA and protein levels decreased within the tumor tissue; a lower expression of Sox15 was related to bigger tumor size and poorer prognosis." (PMID 35392235, 2022). "The expression analysis of the Sox15 promoter methylation indicated that the CpG sites in the Sox15 promoter region were hypermethylated in the tumor samples and HCC cell lines." (PMID 35392235, 2022). "According to this report, SOX15 is underexpressed in TC tumor cells and cell lines under the influence of miR-147b and silencing of SOX15 via miR-147b activates the Wnt/β-catenin pathway." (PMID 34603557, 2021). "In accordance with the previous results, we observed a significant downregulation of the SOX15 gene in the PTC tumor samples compared to normal tissue." (PMID 34603557, 2021). "PPP4R1L and SOX15 are both significantly DE between tumor and normal controls (Bonferroni-corrected P-value = 3.42 × 10−7, 2.01 × 10−14, respectively)." (PMID 31029062, 2019). "This negative regulation of cancer cell proliferation is consistent with our results of SOX15 expression reducing tumor growth, providing additional evidence of a potential suppressor role for SOX15 in tumorigenesis." (PMID 25594027, 2014). "The SOX15 regulon is activated in all tumor subpopulations except T3." (PMID 39223689, 2024). "A number of the identified tumour-associated antigens are known to signal via this cascade, HMGN5, TFG, MAEL, SOX15 and Dicckopf-1, the latter of which has been investigated in numerous other biomarker signatures and like TFG interacts via the Wnt co-receptor LRP6." (PMID 34728792, 2022). "In addition, under in vivo conditions, Sox15 overexpression significantly inhibited the tumor growth as measured by tumor size and weight." (PMID 35392235, 2022). "As a member, SOX15 has acted as a tumor suppressor in the digestive and urinary systems." (PMID 35922412, 2022). "To summarize, Sox15 played a tumor suppressor role within the HCC via the inactivated Wnt pathway." (PMID 35392235, 2022). "We detected the SOX15 transcript in both tumor and normal tissue samples." (PMID 34603557, 2021). "The tumor suppressive action of SOX15 may be mediated through its downregulation of Wnt pathway components." (PMID 31583280, 2019). "Our observation of SOX15 disruption was consistent with Knudson's two-hit hypothesis for tumor suppressor gene inactivation." (PMID 25594027, 2014). "However, overexpressing SOX15 will reverse the effect of AOC1 on tumor growth." (PMID 35922412, 2022). "To deduce a potential mechanism through which SOX15 may exert its tumor suppressive effects, we turned our attention to the Wnt pathway since other SOX family members are known to regulate Wnt/β-catenin signaling and our pathway analysis suggested a potential role for SOX15 in this pathway." (PMID 25594027, 2014). "Following validation of SOX15 downregulation in clinical PDAC tumors, we performed experiments demonstrating that SOX15 exerts tumor suppressor properties in vitro and in vivo." (PMID 25594027, 2014).
tumor (continued). "Specifically, re-expression of SOX15 in PDAC lines with undetectable endogenous levels resulted in significantly reduced cell viability and tumor growth." (PMID 25594027, 2014). "Although in our study downregulation in SOX15 expression was not correlated with miR-375 overexpression, we detected a statistically significant increase in miR-375 expression in tumor samples compared to noncancerous ones." (PMID 34603557, 2021).
cancer (9 papers, 2014 to 2025). A tumor composed of atypical neoplastic, often pleomorphic cells that invade other tissues. "Sox15 expression is reduced by DNA methylation in many cancers like pancreatic, endometrial, colorectal cancers, and glioma." (PMID 35392235, 2022). "Based on such findings, Sox15 mRNA level decreased within varieties of cancer, consistent with studies." (PMID 35392235, 2022). "Colony formation assays in vitro also verified that supplementing SOX15 can enhance the cancer suppression effect of AOC1." (PMID 35922412, 2022). "SOX family members, including SOX4, SOX9, and SOX15, are very often studied in relation to cancer and were observed to be related to the suppression of the Wnt/β-catenin pathway." (PMID 35328735, 2022). "Further supporting this concept, our pan-cancer analysis of SOX15 gene expression showed it was recurrently downregulated in multiple cancer types with high frequencies of disruption (≥ 80%), including colon, stomach, prostate, and uterine cancers." (PMID 25594027, 2014). "In cancer, SOX15 overexpression was found to inhibit the proliferation of human testicular embryonic carcinoma cells." (PMID 25594027, 2014). "Additionally, SOX15 is repeatedly underexpressed among cancer cell lines, including colon, prostate, stomach, and uterine cancers, and overexpressed in some subsets of lung carcinomas." (PMID 38132479, 2023). "The expression of Sox15 was examined by GEPIA in a variety of cancers." (PMID 35392235, 2022). "Upregulation of Sox15 could repress cancer development by suppressing cell growth, invasion, and migration or by promoting cell apoptosis." (PMID 35392235, 2022). "A recent pseudogene-gene (PGG) functional association analysis indicated that miR-375 may also regulate SOX15 expression in different cancer types." (PMID 34603557, 2021). "Much remains to be learned about SOX15 function in development, cell differentiation, and cancer." (PMID 25594027, 2014). "In contrast to other members of the SOX family, function of the SOX15 gene is not well defined in cancer." (PMID 34603557, 2021). "Collectively, our pan-cancer expression analysis and functional validation of SOX15 in PDAC, suggests that SOX15 may be involved in multiple cancer types." (PMID 25594027, 2014).
SOX15 also shares sentences with these, for which no sentence is quoted: leukemia (2 papers); adenocarcinoma (1); esophagus tumors (1); germ cell tumor (1); hepatocellular carcinoma (1); laryngeal carcinoma (1); muscle disorders (1); neurological disorders (1); Obesity (1); thymoma (1); type 2 diabetes (1).